SDHA (succinate dehydrogenase complex flavoprotein subunit A)
Diseases named in the same sentence as SDHA in open-access papers (continued):
Sharing a sentence is not in itself a finding about the gene and the disease.
cancer (continued). "Thus, our findings suggest the PIKE-A/STAT3/FTO/SDHA axis as promising anti-cancer treatment targets." (PMID 36232604, 2022). "In the proband and affected brother, the Thr124Ala variant in PARP1 and the Thr535Ser variant in TRAP1 are of particular interest because like SDHA, these proteins impact mitochondrial function, and defects in PARP1 and TRAP1 have been associated with cancer risk or CAKUT." (PMID 30680959, 2019). "Silencing of expression of the SDHA gene resulted in a decrease of growth rate of cancer cells." (PMID 26017754, 2015). "Some cancer types show a significant association with mutations in well‐known cancer predisposing genes, that is, ovarian cancer in BRCA1/2, whereas new associations were revealed, such as loss of function mutations in BUB1B in lung cancer and in SDHA in melanoma." (PMID 39118233, 2024). "Furthermore, our study definitely confirms the highly relevant association between germline SDHA pathogenic variants and GIST onset, which is supported by many previous studies reporting the development of GIST as the only cancer disease in SDHA germline-variant carrier population." (PMID 35059314, 2021). "Calculating the hazard ratio (HR) of high combined SDHA and SDHB expression across 33 cancer types in TCGA, we found significantly increased mortality risk in only two cancers, with AML being one." (PMID 41350470, 2025). "A high level of SIRT5 desuccinylates SDH and reduces its activity promoting cancer cell proliferation, while SIRT5 silencing results in hyper-succinylation of SDHA and reactivates it, thus preventing the growth of cancer cells." (PMID 36010594, 2022). "Specific missense mutation matches have been found to six proteins from the COSMIC Cancer Gene Census database (FLNA, RPL22, SDHA, NFATC2, NPM1, and CLTCL1)." (PMID 31316139, 2019). "TERT, SDHA and RICTOR had the most frequent copy number gains (26.4%, 25.7% and 23.6% of all cases, respectively), with significant enrichment in carcinomas." (PMID 27873319, 2017). "This is supported by our data showing a significantly correlation of proliferating cancer cells with both glycolysis-related proteins (GLUT-1, TKTL1), and OXPHOS-related enzymes (SDHA, SDHB, ATP synthase)." (PMID 25048361, 2014). "In comparison to normal tissue and hyperplasia a significantly (p < 0.05) increased expression of IGF-R1β, GLUT-1, HK 2, TKTL1, LDHA, SDHA, SDHB, and ATP synthase was observed in cancer cells of OSCC." (PMID 25048361, 2014). "For investigation of proliferating cancer cells and its relation to metabolic characteristics, we performed correlation analysis of Ki-67 with GLUT-1, HK 2, LDHA, TKTL1, SDHA, SDHB, and ATP synthase in OSCC." (PMID 25048361, 2014). "Despite original reports on the essentiality of SDHAF2 in flavination of CII catalytic subunit SDHA and its established role in heritable paraganglioma, CRISPR-Cas9–mediated knockout studies using popular human cancer-derived cell lines showed that flavination of SDHA occurs in its absence." (PMID 40815660, 2025). "Six of these PGVs were in cancer predisposition genes (ATR, CHEK2 (3x), SDHA and MITF) without an established association with familial glioblastoma." (PMID 41168197, 2025). "We found that the mRNA expression level of SDHA was higher in cancer tissues or cells than in non-cancerous tissues or mammary epithelial cell in TCGA dataset, BC clinical specimens and BC cell lines, respectively." (PMID 40119440, 2025).
cancer (continued). "Two of the 77 patients pursued genetic testing due to cascade testing for an LPV/PV in a non-PGL/PCC gene, and because they underwent pan-cancer panel testing, were identified to have an SDHA and an NF1 LPV/PV, respectively." (PMID 39539798, 2024). "While the bacterial FrdA-SdhE and SdhA-SdhE complexes have little buried surface area and can readily disassociate, the human SDHA–SDHAF2 complex is highly stable, long-lived, and appears to accumulate in cancer cell lines." (PMID 37119852, 2023). "Here, we found that PIKE-A promoted SDHA expression via increasing FTO expression through activation of STAT3 signaling and maintaining mitochondrial membrane potential, leading to promoting cancer cell proliferation." (PMID 36232604, 2022). "Third, from our in silico gene deletion analysis, we identified Sterol O-Acyltransferase 1 (SOAT1), methylmalonyl-CoA mutase (MUT), and isozymes of succinate dehydrogenase (SDHA, SDHB, SDHC, and SDHD) as having a significant effect (p-value < 0.05) in cancer as compared to normal samples." (PMID 33396819, 2020). "However, they shared with carcinomas a similar prevalence of copy gains in several genes, including the chromosome 5p genes TERT, SDHA, and RICTOR, but also SRC and MYCL." (PMID 27873319, 2017). "Given the induction of a pseudohypoxic response that can be reversed by re-expressing SDHA and FH, we asked whether ARRB1 might have broader effects on cancer cell metabolism." (PMID 24837709, 2014). "With specific regard to SDHA and SDHB, vitamin E (α-tocopheryl succinat, target: respiratory complex II in mitochondria) and resveratrol (target: respiratory complex V in mitochondria, ATP synthase) were shown to induce apoptosis in cancer cells." (PMID 25048361, 2014). "Consequently, we propose that high levels of SDHA and LRPPRC could serve as novel biomarkers of high-OXPHOS tumors to guide personalized cancer therapy." (PMID 40563592, 2025). "In some situations where an individual has had germline genetic testing for another indication but does not have a personal history of cancer, an SDHA PGV may be identified." (PMID 35260474, 2023). "Indeed, the subassembly of complex II containing SDHA and SDHAF2 can be observed in cancer cells." (PMID 36089066, 2022). "Notably, two of the proteins, SDHA and IDH3A, key components of TCA, are involved in regulating energy metabolism in the mitochondria and considered to be actionable therapeutic targets in several cancers." (PMID 35463978, 2022). "Until recently, no genetic link between SDHA and cancer could be established." (PMID 22974104, 2012). "Importantly, our findings revealed that the concomitant overexpression of SDHA and LRPPRC could be considered as novel biomarkers for identifying tumors that rely on high OXPHOS metabolism, offering a potential avenue for tailoring personalized cancer treatments." (PMID 40563592, 2025). "As anticipated, overall SDHA levels were similar among the cell types (quantitative data not shown), but SDHB levels were 1.8-fold lower in cancer compared to adjacent normal tissues." (PMID 37945749, 2023).
infection (16 papers, 2009 to 2025). The state of being infected such as from the introduction of a foreign agent such as serum, vaccine, antigenic substance or organism. "Additionally, a previous infection study reported an association of sdhA-deficient L. pneumophila with increased dendritic cell death." (PMID 28873330, 2018). "More recently, it was also found that while SdeA family of LP effectors guard LCV in the first few hours of infection, SdhA plays an essential role of guarding LCV at later stages of infection." (PMID 37923743, 2023). "sdhA was upregulated gradually over the time points studied, expression levels were significantly higher at 24 to 48 hours after infection." (PMID 28873330, 2018). "Among the metabolic genes, Transketolase (TKT) and Succinate dehydrogenase subunit A (SDHA) were down-regulated by either KSHV-infection or CoCl2 treatment." (PMID 29746587, 2018). "The expression of flaA decreased from −3.6-fold to −6.7-fold over time, whereas the expression of sdhA was upregulated at all time points, increasing from a 1.5-fold upregulation at 12 hours to 8.1-fold at 48 hours post-infection." (PMID 28873330, 2018). "By contrast, sdhA and sidF exhibited changes of <2-fold at most time points, except for a 4.3-fold downregulation of sdhA at 48 hours post-infection." (PMID 28873330, 2018). "Interestingly, deletion of SdhA alone results in defective growth in mouse macrophages while deletion of the two paralogues SidH and SdhB does not cause any significant growth phenotype indicating that these paralogs may have different functions during infection." (PMID 37923743, 2023). "On the contrary, SdhA is a requirement for pathogenicity in E. coli, to stabilize the vacuole integrity during replication in the intracellular pathogen (like B. ovis) Legionella pneumophila, and its reduction is detected early during infection in B. abortus." (PMID 35315701, 2022). "In contrast, the levels of nuclearly encoded succinate dehydrogenase A (SDHA), part of respiratory complex II, were not significantly changed by infection." (PMID 27025248, 2016). "In conclusion, RPL30 and SDHA could be used as reference genes for the standardization of in CEF gene response to the infection with ALV-J, whereas commonly used ACTB and GAPDH are unsuitable to be reference genes in ALV-J/CEF settings." (PMID 24099561, 2013). "In the current study, M1 and M2 subsets increased their glycolytic metabolism upon infection with Stm, as demonstrated by increased extracellular acidification rates and lactate production and reduced succinate dehydrogenase complex subunit A (SDHA) mRNA levels." (PMID 34552598, 2021). "The RT-qPCR data were normalized to the mean value of the transcriptionalactivity of two housekeeping genes (GAPDH andSDHA) since their expression profile was only marginallyaffected (SDHA; log2 = 0.2, P = 0.3; GAPDH;log2 = 0.2, P = 0.04) upon AAV2 infection." (PMID 38837381, 2024). "The expression profiles of flaA and sdhA, together with the reduced expression of CASP genes in L. pneumophila-infected THP-1 cells, indicated that cell death pathways were inhibited after infection." (PMID 28873330, 2018). "Due to the attenuated infection, HSV-1 induced host shutoff, as measured by RNA levels of the housekeeping genes POLR1B, SDHA, TBP, and PPIA, which were reduced." (PMID 29089033, 2017). "Moreover, the mRNA expression of citrate synthase (CS) and succinate dehydrogenase subunit A (SDHA), two key enzymes in the tricarboxylic acid cycle (TCA), was found to be distinctly higher post infection (both P < 0.001)." (PMID 34552973, 2021). "Macrophages infected with mutants lacking sdhA gene trigger Aim2-dependent activation of caspase-1, secretion of IL-1β and pyroptosis, which is reversible by infection with genetically complemented bacteria." (PMID 24324933, 2013).
infection (continued). "By contrast, the effector SdhA is required to prevent macrophage cell death during infection by a mechanism that is not understood, and the cell death induced by an sdhA mutant greatly reduces bacterial replication in macrophages." (PMID 19521510, 2009).
mitochondrial disease (11 papers, 2017 to 2025). "Autosomal mutations in SDHA have been linked to mitochondrial dysfunction and mitochondrial diseases." (PMID 39757625, 2025). "This is analogous to the situation in humans in which SdhA mutations most commonly result in clinical outcomes reminiscent of other mitochondrial diseases." (PMID 35563430, 2022). "The genotypes and phenotypes associated with SDHA‐related mitochondrial disease are variable, with both dominant and recessive inheritance being reported." (PMID 33960148, 2021). "Of historical note is the fact that pathogenic variants in SDHA represent the very first cause of Mendelian mitochondrial disease." (PMID 33162331, 2020). "To date, eleven different null SDHA alleles have been reported in primary mitochondrial disease presentations." (PMID 33162331, 2020). "The first nuclear mitochondrial gene mutation was identified in 1995 in SDHA, encoding a structural subunit of complex II 25, and there has been monumental progress in the discovery of mitochondrial disease candidate genes since then." (PMID 27659608, 2017). "This shows that, as in the case of other mitochondrial disease phenotypes in the Dictyostelium model, all of the SdhA phenotypes result from chronic AMPK hyperactivity." (PMID 35563430, 2022). "Partial loss of SdhA resulted in mitochondrial dysfunction and AMPK-mediated phenotypic outcomes similar to those in previously studied D. discoideum mitochondrial disease models." (PMID 35563430, 2022). "Although complex II deficiencies are exceedingly uncommon (almost 2–8% of mitochondrial disease cases), either homozygous or heterozygous pathogenic variants are reported in SDHA, SDHB, and SDHD genes, leading to some primary mitochondrial disease such as Leigh or Leigh-like syndrome." (PMID 35160083, 2022). "Mutations in genes encoding for either structural subunits or assembly factors have been described (SDHA, SDHB, SDHD, and SDH assembly factor 1 (SDHAF1) for mitochondrial diseases; SDHD, SDHC, SDHB, SDHA, and SDHAF2 for hereditary paragangliomas)." (PMID 30030362, 2018).
neurodegenerative disease (9 papers, 2012 to 2025). A disorder of the central nervous system characterized by gradual and progressive loss of neural tissue and neurologic function. "Recent studies have shown that succinate dehydrogenase and SDHA were suppressed in the brains of neurodegenerative disease patients or animal models." (PMID 27788166, 2016). "In contrast, in PF tissue, genes like ATP5F1A, ATP5PO, SDHB, NDUFS8, SDHA, and COX5A play roles within the neurodegenerative disease pathway, and PF tissue has a positive impact on the process related to degenerative diseases." (PMID 40136641, 2025). "IF regulates lipid metabolism primarily via genes including FABP4, WNT10B, PCK1, PLIN1, LEPR, and ADIPOQ, providing energy for cold adaptation, whereas PF positively influences in vivo degenerative diseases mainly through genes such as ATP5F1A, ATP5PO, SDHB, NDUFS8, SDHA, and COX5A." (PMID 40136641, 2025). "KEGG pathway analysis revealed that KRG also influences neurodegenerative disease-related pathways by alleviating the expression of four proteins suppressed by MPTP administration, MAPK1, SDHA, mitocholdrial cytochrome b-c1 complex subunit Rieske and cytochrome c oxidase (COX) subunit VIaL." (PMID 27788166, 2016).
gastrointestinal tumors (1 paper, 2023). "Consistently, immunohistochemical staining in SDHA-related gastrointestinal tumors reveals normal SDHA but lowered SDHB expression." (PMID 37945749, 2023).
immune diseases (1 paper, 2022). "Abnormalities of SDH activity, which induce immune diseases, are usually associated with metabolic dysfunction, such as the reduced activity of SDHA and SDHB." (PMID 36354983, 2022).
respiratory diseases (1 paper, 2012). "Since in the most cases, Gram-negative and Gram-positive bacteria are observed together in respiratory diseases, HPRT1, YWHAZ and SDHA might be an appropriate set of reference genes for the gene expression normalization in AM studies." (PMID 22340302, 2012).
SDHA also shares sentences with these, for which no sentence is quoted: head and neck paraganglioma (6 papers); Neurological Disease (5); myopathy (3); Encephalopathy (2); endocrine disease (2); endocrine tumors (2); leukodystrophy (2); liver cancer (2); metabolic disorder (2); multiple endocrine neoplasia type 2 (2); nematode infections (2); neuroendocrine tumors (2); neurofibromatosis type 1 (2); pituitary tumour (2); prion disease (2); tumor predisposition syndrome (2); Von Hippel Lindau syndrome (2); acromegaly (1); adrenocortical adenoma (1); astrocytomas (1); basal cell carcinoma (1); bone metastasis (1); brain diseases (1); Cachexia (1); Carney-Stratakis syndrome (1); cholesteatoma (1); clear cell carcinoma (1); cognitive decline (1); colitis (1); developmental delay (1).
A further 56 diseases each share a sentence with SDHA in 1 paper.